GPR4 (G protein-coupled receptor 4)
Diseases named in the same sentence as GPR4 in open-access papers (continued):
Sharing a sentence is not in itself a finding about the gene and the disease.
endothelial dysfunction (2 papers, 2024 to 2025). In vascular diseases, endothelial dysfunction is a systemic pathological state of the endothelium (the inner lining of blood vessels) and can be broadly defined as an imbalance between vasodilating and vasoconstricting substances produced by (or acting on) the endothelium. "We also acknowledge involvement of another receptor, GPR4, in endothelial dysfunction caused by medium acidosis, while our data indicate that GPR4 was not involved in EC permeability and inflammation caused by LPS." (PMID 41193514, 2025). "Moreover, assessment of pharmacological inhibitors of GPR68 and GPR4 on acidic pH-caused endothelial dysfunction further assisted to delineate the involvement of these receptors." (PMID 39768215, 2024).
ischemia (2 papers, 2020). A hypoperfusion of the BLOOD through an organ or tissue caused by a PATHOLOGIC CONSTRICTION or obstruction of its BLOOD VESSELS, or an absence of BLOOD CIRCULATION. "GPR4 KO mice had less observable tissue edema in the tourniquet-affected limb following the ischemia and reperfusion event when compared with WT mice." (PMID 32058960, 2020). "Furthermore, evaluation of the contribution of GPR4 in the hindlimb post-ischemia/reperfusion inflammatory response supports the role for GPR4 in vascular permeability and inflammation." (PMID 32058960, 2020).
preeclampsia (2 papers, 2023 to 2024). Preeclampsia is a hypertensive disorder of pregnancy that is characterized by new-onset hypertension with proteinuria presenting after 20 weeks of gestation, and depending on mild or severe forms may initially present with severe headache, visual disturbances, and hyperreflexia. "Given that preeclampsia occurs in 8% of all pregnancies with potentially devastating consequences, it seems that genetic variants of GPR4 are worthwhile studying in the context of preeclampsia." (PMID 38340167, 2024). "Two other studies have investigated a role for GPR4 in trophoblasts and find that GPR4 expression was upregulated in preeclampsia (PE) placentas compared to healthy placentas." (PMID 38340167, 2024).
adenocarcinoma in situ (1 paper, 2023). A lesion in which the normally situated glands are partially or completely replaced by atypical cells with malignant characteristics. "Histological analyses of the colon tissue sections revealed that colon dysplasia (Dys) and adenocarcinoma in situ (AIS) were induced in both the WT and GPR4 KO AOM/DSS mice." (PMID 37894341, 2023).
Alzheimer disease (1 paper, 2024). A progressive, neurodegenerative disease characterized by loss of function and death of nerve cells in several areas of the brain leading to loss of cognitive function such as memory and language. "The link to Alzheimer’s disease was established in a transcriptome-wide association study that identified GPR4 as a potential predictive biomarker, most likely due to pro-inflammatory effects on the immune system." (PMID 38340167, 2024).
autoimmune disease (1 paper, 2024). A disorder resulting from loss of function or tissue destruction of an organ or multiple organs, arising from humoral or cellular immune responses of the individual to their own tissue constituents. "The pH-sensing receptors, TDAG8 and GPR4, are mainly expressed in the immune cells and modulate inflammatory signalling in various diseases including autoimmune diseases of the CNS such as MS." (PMID 38527054, 2024).
Bradykinesia (1 paper, 2021). Bradykinesia literally means slow movement, and is used clinically to denote a slowness in the execution of movement (in contrast to hypokinesia, which is used to refer to slowness in the initiation of movement). "The pharmacological inhibition of GPR4 improved MPTP-induced bradykinesia in mice." (PMID 33925146, 2021).
Cognitive impairment (1 paper, 2021). Abnormal cognition is characterized by deficits in thinking, reasoning, or remembering. "As a result, mice develop motor deficits and cognitive impairments, which can be restored by the pharmacological inhibition of GPR4." (PMID 33925146, 2021).
colon adenocarcinoma (1 paper, 2025). "Enhanced expression of GPR4 mRNA is detected in human cancers, including gastric cancer and colon adenocarcinoma, and CRC." (PMID 40397803, 2025).
colorectal adenocarcinoma (1 paper, 2016). The most common type of colorectal carcinoma. "The average rank scores (ARS), Bonferroni correction adjusted P-values were synthesized, and GPR4 was upregulated in kidney clear cell renal cell carcinoma, SCCHN and colorectal adenocarcinoma." (PMID 27078157, 2016).
Crohn disease (1 paper, 2023). A gastrointestinal disorder characterized by chronic inflammation involving all layers of the intestinal wall, noncaseating granulomas affecting the intestinal wall and regional lymph nodes, and transmural fibrosis. "Previous studies have shown that GPR4 gene expression is upregulated in both ulcerative colitis (UC) and Crohn’s disease (CD) patient intestinal samples compared with normal intestinal tissue." (PMID 37894341, 2023). "GPR4 expression is positively correlated with fibrogenic gene expression in highly fibrotic intestine lesions obtained from Crohn’s disease (CD) patients." (PMID 37894341, 2023).
dysplasia (1 paper, 2023). A usually neoplastic transformation of the cell, associated with altered architectural tissue patterns. "In this context, GPR4 can contribute to chronic inflammation and tumor development, which can feedforward in the inflammation–dysplasia–carcinoma axis, resulting in CAC development." (PMID 37894341, 2023). "Interestingly, the distribution of dysplasia and adenocarcinoma in the WT and GPR4 KO AOM/DSS mice showed a 9% decrease in adenocarcinomas in the GPR4 KO mice compared with the WT mice (85% vs. 94%, respectively)." (PMID 37894341, 2023).
idiopathic pulmonary fibrosis (1 paper, 2022). Idiopathic pulmonary fibrosis (IPF) is a nonneoplastic pulmonary disease that is characterized by the formation of scar tissue within the lungs in the absence of any known cause. "To identify receptors of interest, we examined the protein expression profiles of TDAG8, OGR1, G2A, and GPR4 in primary human lung fibroblasts isolated from patients with or without a diagnosis of Idiopathic Pulmonary Fibrosis (IPF)." (PMID 36233248, 2022).
infarction (1 paper, 2020). A localised pathological necrosis of tissue resulting from obstruction of the blood supply usually by a thrombus, an embolus, or vascular torsion. "Under the same tMCAO protocol, the deficiency of neither OGR1 nor GPR4 showed any significant effect on the infarction size." (PMID 33057165, 2020).
influenza (1 paper, 2025). An acute viral infection of the respiratory tract, occurring in isolated cases, in epidemics, or in pandemics; it is caused by serologically different strains of viruses (influenzaviruses) designated A, B, and C, has a 3-day incubation period, and usually lasts for 3 to 10 days. "We summarized some potential new protein targets associated with obesity that exacerbate influenza infection in respiratory disease, including α/β-hydrolase domain 6, Histone deacetylase 6, G-protein-coupled receptor 4, and so on, which can affect obesity and influenza." (PMID 40863240, 2025).
intestinal tumor (1 paper, 2023). "We found that GPR4 contributed to chronic intestinal inflammation and heightened DSS/AOM-induced intestinal tumor burden." (PMID 37894341, 2023).
kidney tumors (1 paper, 2020). "GPR4 appeared up-regulated in cholangiocarcinoma, down-regulated in cervical and lung cancers, and increased or decreased in kidney tumors depending on the kind of cancer." (PMID 33113952, 2020). "In cancer, GPR4 gene overexpression was initially detected in a variable proportion of breast, ovarian, colon, liver and kidney tumors, but not in lung or prostate tumors." (PMID 33113952, 2020).
lymphoma (1 paper, 2013). A malignant (clonal) proliferation of B- lymphocytes or T- lymphocytes which involves the lymph nodes, bone marrow and/or extranodal sites. "Our RT-PCR results also showed that among the proton-sensing GPCRs, TDAG8 and G2A have the highest expression levels and OGR1 has a relatively low expression, whereas GPR4 is barely detectable in U937 lymphoma cells." (PMID 24152439, 2013).
medulloblastoma (1 paper, 2018). A malignant, invasive embryonal neoplasm arising from the cerebellum. "The frequency of medulloblastoma patients in these four groups were 34% for GPR4, 28% for SHH, 27% for GPR3, and 11% for WNT." (PMID 30279357, 2018). "In 2012 a general consensus was reached regarding the existence of only four molecular subgroups of medulloblastomas, termed WNT, SHH, Group 3 (GPR3), and Group 4 (GPR4)." (PMID 30279357, 2018).
memory impairment (1 paper, 2021). "We investigated whether the pharmacological inhibition of GPR4 had any effects on memory impairments and behavioral deficits by performing rotarod, Y-maze, and pole tests." (PMID 33925146, 2021).
metastatic disease (1 paper, 2018). "At diagnosis, 24% of patients have a metastatic disease and the highest frequency of metastatic disease was observed among GPR3 and GPR4." (PMID 30279357, 2018).
narcolepsy (1 paper, 2009). A sleep disorder characterized by a tendency for excessive sleepiness during the day which occurs even after adequate sleep in the nighttime. "The other downregulated genes that were found, or previously known to express elsewhere (eg NPY, GPR4), may reflect physiologically important network remodeling in narcolepsy." (PMID 19158946, 2009).
neuroblastoma (1 paper, 2020). Neuroblastoma (NB) is the most common solid, extracranial childhood tumor. "In this study, we investigated the role of GPR4 in the 1-methyl-4-phenylpyridinium ion (MPP+) and hydrogen peroxide (H2O2)-treated apoptotic cell death of stably GPR4-overexpressing and stably GPR4-knockout human neuroblastoma SH-SY5Y cells." (PMID 33053856, 2020).
prostate carcinoma (1 paper, 2013). A carcinoma that arises from epithelial cells of the prostate gland. "Together with our published studies in prostate cancer cells, the results of the current study indicate that OGR1 and GPR4 are likely to have opposing roles in cancer cells, suggesting that they are coupled to different sets of down-stream signaling molecules." (PMID 23663350, 2013).
renal cell carcinoma (1 paper, 2023). "Further, renal cell carcinomas and epithelial ovarian carcinomas showed a correlation between GPR4, VEGFA and microvascular density." (PMID 36611126, 2023).
rheumatoid arthritis (1 paper, 2024). A chronic, systemic autoimmune disorder characterized by inflammation in the synovial membranes and articular surfaces. "Finally, GPR4 has also been linked to rheumatoid arthritis by affecting synovial mast cell function." (PMID 38340167, 2024). "In addition to GPR4, TDAG8 has also been implicated in rheumatoid arthritis." (PMID 38340167, 2024).
skin cancer (1 paper, 2020). "In this study, we have examined the expression profiles of the pH-GPCRs GPR4 (GPR19), TDAG8 (GPR65), OGR1 (GPR68) and G2A (GPR132) on different types of common skin tumors, SCC, MM, NCN and BCC." (PMID 32948783, 2020).
Stroke (1 paper, 2024). Sudden impairment of blood flow to a part of the brain due to occlusion or rupture of an artery to the brain. "Finally, RNA sequencing found that transient stroke induction increased expression levels of GPR4 and TDAG8 but not OGR1, and OGR1 deletion did not affect expression levels of GPR4 or TDAG8 under control or ischaemic conditions, suggesting that OGR1 does not affect GPR4 or TDAG8 expression." (PMID 38340167, 2024).
synovitis (1 paper, 2022). Inflammation of a synovial membrane. "Synovitis and macrophage infiltration were notably decreased in Gpr4−/− mouse synovium compared to WT mice." (PMID 35165253, 2022).
Thromboembolism (1 paper, 2020). The formation of a blood clot inside a blood vessel that subsequently travels through the blood stream from the site where it formed to another location in the body, generally leading to vascular occlusion at the distant site. "Inhibition of GPR4 may lessen inflammatory response, blood cell-endothelium adhesion and aggregation, and thromboembolism." (PMID 33553219, 2020).
tumor (27 papers, 2013 to 2025). "Gpr4‐deficient mice showed a significantly increased number of NKp46+ cells in tumor tissue, and increased numbers of NK cells were confirmed by qPCR and flow cytometry." (PMID 40397803, 2025). "In the azoxymethane (AOM)/dextran sodium sulfate (DSS) model of CRC, Gpr4‐deficient mice showed significantly reduced tumor progression and number of apurinic/apyrimidinic (AP) sites." (PMID 40397803, 2025). "In the MC38 model, Gpr4‐deficient mice showed significantly reduced tumor size and weight compared to wild‐type (WT) mice." (PMID 40397803, 2025). "Evaluation of tumor size revealed significantly smaller tumors and a reduced number of Ki67‐positive cells in Gpr4‐deficient mice compared to WT mice." (PMID 40397803, 2025). "In parallel to the increased influx of NK cells and NKT cells in GPR4‐deficient animals, we observed a significant reduction of neutrophils and inflammatory monocytes in tumor tissue, accompanied by reduced pro‐inflammatory IL6 levels." (PMID 40397803, 2025). "Taken together, our results from the orthotopic AOM/DSS model of CRC showed that GPR4 deficiency significantly attenuated spontaneous tumor formation and tumor progression, supporting and extending the results from the MC38 model." (PMID 40397803, 2025). "The angiogenic response to VEGF, allograft tumor growth, and angiogenesis were all found to be reduced in GPR4-deficient mice." (PMID 39336742, 2024). "Tumor blood vessel density was markedly reduced in mice deficient in GPR4, which correlated with increased tumor necrosis and reduced tumor cell proliferation." (PMID 37894341, 2023). "The in-vivo and in-vitro studies indicated that GPR4 induces angiogenesis at acidic pH, a hallmark of tumor progression." (PMID 27078157, 2016). "The GPR4 deficiency in mice, however, has been reported to reduce the growth of tumor allografts by impairing angiogenesis from the host mice." (PMID 24367336, 2013). "Loss of GPR4 in mice is linked to reduced tumor angiogenesis and tumor development." (PMID 40397803, 2025). "Similarly, intestinal inflammation, development of CRC, and tumor angiogenesis were reduced in GPR4-deficient mice compared to WT control." (PMID 38514581, 2024). "However, GPR4 deficiency in murine models reduces tumour allograft growth by interfering with angiogenesis since GPR4 is expressed on endothelial cells; however, overexpression of GPR4 can transform fibroblasts." (PMID 36046070, 2020). "In the tumor microenvironment, mesenchymal acidic pH can activate GPR4 to regulate the behavior of tumor cells." (PMID 40689396, 2025). "Overall, our data indicate enhanced tumor cell clearance in Gpr4−/− mice compared to WT through increased cytotoxic cell activity." (PMID 40397803, 2025). "Results from these analyses confirmed slower tumor growth, significantly reduced tumor size in vivo, and tumor weight ex vivo in Gpr4−/− mice." (PMID 40397803, 2025). "It is not yet fully established how the augmented presence of NK cells in the tumor infiltrate of Gpr4−/− animals is brought about." (PMID 40397803, 2025). "With respect to other cells of the immune infiltrate, CD3‐positive T cells overall were significantly increased in tumor tissue of Gpr4−/− mice compared to WT (single, viable, CD45+, B220−, CD3+)." (PMID 40397803, 2025). "Lysophosphatidylcholine binds to G protein-coupled receptors (G2A/GPR4), activating signaling pathways that promote cancer cell proliferation, migration, and survival, thereby enhancing tumor invasiveness and metastasis." (PMID 41347169, 2025). "The increased number of CD3+ lymphocytes concomitant with reduced neutrophils in tumor tissue of Gpr4−/− animals leads to a significantly reduced neutrophil/CD3+ cell ratio compared to WT." (PMID 40397803, 2025). "IHC revealed significantly enhanced staining for IL2 protein in MC38‐luciferase tumor tissue from Gpr4−/− mice compared to WT mice." (PMID 40397803, 2025).